RRM2 (ribonucleotide reductase regulatory subunit M2)
Diseases named in the same sentence as RRM2 in open-access papers (continued):
Sharing a sentence is not in itself a finding about the gene and the disease.
Ewing sarcoma (9 papers, 2016 to 2025). A small round cell tumor that lacks morphologic, immunohistochemical, and electron microscopic evidence of neuroectodermal differentiation. "MYBL2 has been identified as a direct target of EWSR1::FLI1 with germline polymorphisms associated with activation in Ewing sarcoma and RRM2 overexpression is associated with poor prognosis Ewing sarcoma." (PMID 36793594, 2023). "In previous work, we identified that Ewing sarcoma cell lines require active protein synthesis to maintain a stable level of the ribonucleotide reductase M2 (RRM2) protein, which is a potential therapeutic target in Ewing sarcoma tumors." (PMID 38933441, 2024). "In particular, the RRM2 subunit of RNR is expressed at high levels in Ewing sarcoma cells relative to other cancers." (PMID 27557498, 2016). "Hydroxyurea, a well-established inhibitor of RRM2, inhibited the growth of Ewing sarcoma cells at concentrations (IC50 range 165-300 μM) that are significantly lower than concentrations typically used for cell cycle synchronization (> 1 mM)." (PMID 27557498, 2016). "We then used siRNA to knockdown RRM2 in Ewing sarcoma cells to complement the small-molecule studies." (PMID 27557498, 2016). "Notably, expression of this siRNA-resistant RRM2 gene in Ewing sarcoma cells rescued the growth defect and caspase-3/7 activation caused by transfection of si_RRM2_3 and knockdown of endogenous RRM2." (PMID 27557498, 2016). "RRM2 is highly expressed in Ewing sarcoma cells compared to other cancer types (p-value < 0.01) and treatment of Ewing sarcoma cells with ciclopirox resulted in a significant reduction in deoxyribonucleotide levels, as predicted if RRM2 is a target of ciclopirox." (PMID 27557498, 2016). "Finally, to exclude siRNA off-target effects, we generated an Ewing sarcoma cell line that expresses a RRM2 gene, under the control of a doxycycline-inducible promoter, that is resistant to siRNA knockdown." (PMID 27557498, 2016). "To test whether SLFN11 expression modulates the sensitivity of Ewing sarcoma cells to RRM2 knockdown we used siRNA to knockdown both SLFN11 and RRM2 in Ewing sarcoma cells." (PMID 27557498, 2016). "Consequently, we next evaluated whether auranofin and ROS downregulate RRM2 levels in Ewing sarcoma cells." (PMID 38933441, 2024). "In this study, we identified that multiple HDAC inhibitors, including fimepinostat, romidepsin, and panobinostat, downregulate the levels of the RRM1, RRM2, CHK1, and WEE1 proteins in Ewing sarcoma cells and impair DNA replication." (PMID 40478628, 2025). "In this work, we identify that HDAC inhibitors broadly disrupt DNA replication and the response to replication stress in Ewing sarcoma cells by downregulating RRM1, RRM2, CHK1, and WEE1." (PMID 40478628, 2025). "In this study, we identify that HDAC inhibitors more broadly disrupt DNA replication and the cellular response to DNA replication stress by downregulating the expression of RRM1, RRM2, CHK1, and WEE1 in Ewing sarcoma cells." (PMID 40478628, 2025). "We then identified ribonucleotide reductase M2 (RRM2), the iron-dependent subunit of ribonucleotide reductase (RNR), as one mediator of iron chelator toxicity in Ewing sarcoma cells." (PMID 27557498, 2016). "Knockdown of RRM2 with siRNA resulted in a significant reduction in cell growth and activation of caspase-3/7 in Ewing sarcoma cells, but not the other cell lines we tested." (PMID 27557498, 2016). "In previous work, we identified that the iron-dependent RRM2 subunit of ribonucleotide reductase (RNR), which is the rate limiting and iron-dependent enzyme in the synthesis of deoxyribonucleotides and required for DNA replication, is one target of iron chelators in Ewing sarcoma cells." (PMID 33256675, 2020). "Consequently, the toxicity of ATR inhibitors as single agents with Ewing sarcoma cells may, in part, be due to inhibition of RNR by reducing levels of the RRM2 subunit." (PMID 29152060, 2017).
multiple myeloma (8 papers, 2020 to 2024). "Lower PCLAF and RRM2 levels were associated with better survival for patients with myeloma." (PMID 38509117, 2024). "It is also cell permeable, motivating further testing in preclinical trials for use in hRpn13Pru-producing cells, with upregulated PCLAF and RRM2, such as myeloma cells." (PMID 38509117, 2024). "RRM2 silencing has been suggested to inactivate the Wnt/β-catenin signaling pathway by increasing GSK-3β phosphorylation in multiple myeloma." (PMID 35609318, 2022). "Bulk sequencing validation highlights PCC6-specific genes ribonucleotide reductase regulatory subunit M2 (RRM2) as novel prognostic markers in multiple myeloma (MM)." (PMID 36315425, 2022). "A recent study indicated that RRM2 upregulation occurred in multiple myeloma tumors and that RRM2 knockdown inhibited multiple myeloma cell proliferation." (PMID 33123291, 2020). "Recent studies have shown that RRM2 upregulation occurs in multiple myeloma tumors, and RRM2 inhibition can inhibit multiple myeloma cell proliferation." (PMID 33123291, 2020). "Moreover, RRM2 and CDC25A are among a 37 gene product signature for responsiveness to rapamycin and entinostat in myeloma and thereby prognostic of risk and survival." (PMID 38509117, 2024). "We also examined the protein expression of RRM2 in multiple myeloma cells by western blotting." (PMID 35546402, 2022). "Surprisingly, it has been reported that silencing RRM2 inhibits multiple myeloma by targeting the Wnt/β−catenin signaling pathway, implying that RRM2 may be a new therapeutic target for MM." (PMID 34567073, 2021). "Taken together, targeting RRM2 may provide a novel therapeutic strategy for the treatment of multiple myeloma." (PMID 34567073, 2021). "Indeed, the synergistic anti-tumor effect of the combination of 4-hydroxysalicylanilide (targeting RRM2) together with the proteasome inhibitor Bortezomib has been shown in multiple myeloma cell lines, including primary CD138+ cells from Bortezomib-refractory patients." (PMID 36983519, 2023). "XL44 induces apoptosis in myeloma cells with hRpn13 dependency and also targets KEN box proteins PCLAF and RRM2." (PMID 38509117, 2024). "To determine if the anti-myeloma activity of HDS depended on RRM2, we established stable RRM1- and RRM2-knockdown and overexpression MM cell lines." (PMID 35546402, 2022).
sarcoma (8 papers, 2021 to 2026). A usually aggressive malignant neoplasm of the soft tissue or bone. "In addition, wedemonstrated that RRM2 was highly associated with poor prognosis inpatients with sarcoma." (PMID 40834268, 2025). "By analyzing data from TCGA sarcoma cohort, we further confirmeda strong positive correlation between RRM2 and cyclin B1, cyclin E1,and CHEK1 expression, as well as a negative correlation with TP53expression." (PMID 40834268, 2025). "Overall, these results define a link between ROS and protein synthesis in sarcoma cells and identify a mechanistic connection between ROS and the DNA replication (RRM2) and cell cycle regulatory (PLK1) pathways." (PMID 38933441, 2024). "Activation of 4E-BP1 reduces the levels of the oncogenic proteins ribonucleotide reductase M2 (RRM2) and polo-like kinase 1 (PLK1) in Ewing and other sarcoma cell lines." (PMID 38933441, 2024). "In addition, by using the GEPIA online data analysis platform, we found that in the sarcoma dataset (SARC, n=262), patients with high RRM2 gene expression had significantly shorter overall survival than did those with low RRM2 gene expression (P=0.042)." (PMID 40510157, 2025).
adrenocortical cancer (7 papers, 2017 to 2025). "One research indicates that cell cycle dependent RRM2 may serve as proliferation marker and pharmaceutical target in adrenocortical cancer." (PMID 38635758, 2024). "RRM2 exhibits a strong correlation with Ki67 in adrenocortical cancer." (PMID 35248107, 2022). "Regarding the tumor stage, RRM2 expression was significantly associated with Skin Cutaneous Melanoma (SKCM) in stage I group, BRCA, COAD, LUAD, LUSC and PAAD in stage II group, KIRP, LIHC and THCA in stage III group, adrenocortical carcinoma (ACC), KICH, KIRC and TGCT in stage IV group." (PMID 38635758, 2024).
leukemia (7 papers, 2017 to 2025). A malignant (clonal) hematologic disorder, involving hematopoietic stem cells and characterized by the presence of primitive or atypical myeloid or lymphoid cells in the bone marrow and the blood. "In this study, we demonstrate that monobenzone is a potent inhibitor of RNR enzyme activity by targeting RRM2 protein, and thus has significant anti-leukaemia efficacy in vitro and in vivo." (PMID 36230632, 2022). "Several RNR inhibitors are also used in anti-leukaemia therapies, such as hydroxyurea (HU) that targets RRM2 to treat chronic myeloid leukaemia (CML) and AML and the ribonucleoside analogues cytarabine and clofarabine that target RRM1 to treat acute leukaemia." (PMID 36230632, 2022). "In this study, we show that RRM2 expression is strongly correlated with malignant proliferation in patients with AML and that MB is a potent inhibitor of RNR enzymatic activity by targeting the RRM2 protein, thereby possessing significant anti-leukaemia efficacy in vitro and in vivo." (PMID 36230632, 2022).
COVID-19 (6 papers, 2022 to 2024). A disease caused by infection with severe acute respiratory syndrome coronavirus 2. "We found that in the BD–COVID-19 interaction, genes RRM2, IFNAR2, and SLC7A11 and miRNAs hsa-mir-30a-5p, hsa-mir-93-5p, and hsa-mir-192-5p have more significant effects." (PMID 35185890, 2022). "Finally, submodule analysis showed that PRC1, KIFC1, BUB1, MCM6, CCNB2, CDKN3, and RRM2, which were hub-shared genes of silicosis and COVID-19, possessed the highest mCODE scores." (PMID 37278873, 2023). "Increasing evidence indicates that RRM2 plays an essential role in the productive replication of multiple viruses, including HCV, HPV, ALV-J, and COVID-19." (PMID 39766842, 2024). "We successfully identified the shared 6 candidate gene signatures (RRM2, EGF, TMEM252, RARRES1, COL6A3, CUBN) between COVID-19 and AKI." (PMID 37789254, 2023). "The results revealed that 6 key gene signatures (RRM2, EGF, TMEM252, RARRES1, COL6A3, CUBN) were recognized to have great influences on COVID-19 and AKI." (PMID 37789254, 2023). "In our study, seven genes (BUB1, PRC1, KIFC1, RRM2, CDKN3, CCNB2, and MCM6) were involved in the interaction between COVID-19 and silicosis." (PMID 37278873, 2023). "In the COVID-19 dataset, TYMS(AUC:0.952), RRM2(AUC:0.954), CDCA2(AUC:0.946) and TOP2A(AUC:0.958) exhibited good diagnostic efficiency for differentiating the patients with SARS-CoV-2 from healthy controls." (PMID 35958619, 2022). "For the remaining five hub genes (TYMS, CDCA2, TOP2A, RRM2 and IFI44), there are no studies reporting their role in COVID-19 or pSS, which emphasizes its importance in future research." (PMID 35958619, 2022).
small cell lung carcinoma (6 papers, 2019 to 2025). Small cell lung cancer (SCLC) is a highly aggressive malignant neoplasm, accounting for 10-15% of lung cancer cases, characterized byrapid growth, and early metastasis. "It has been found that miR-1 inhibited the proliferation and metastasis of small cell lung cancer via C-X-C chemokine receptor type 4 / forkhead box protein / RRM2 axis." (PMID 38820515, 2024). "For instance, in small-cell lung cancer, miR-1 directly suppresses C-X-C motif chemokine receptor 4 (CXCR4), leading to the subsequent inhibition of FOXM1 and ribonucleotide reductase M2 (RRM2), thereby impeding tumor progression." (PMID 41373864, 2025). "We found that the mRNA expression of RRM1, RRM2, and RRM2B genes were up-regulated in 57.9% (11 of 19), 78.9% (15 of 19), and 0% (0 of 9), respectively, of the Oncomine cancer studies covering the four subtypes of LUSC, LUAD, large cell lung carcinoma (LCLC), and small cell lung carcinoma (SCLC)." (PMID 31637211, 2019).
nasopharyngeal carcinoma (5 papers, 2017 to 2024). A carcinoma arising from the nasopharyngeal epithelium. "In nasopharyngeal carcinoma, RRM2 overexpression enhanced colony formation, as well as cell proliferation, migration and invasion." (PMID 33858512, 2021). "Through our preliminary experiment, a novel chimeric transcript called chimeric transcript RRM2-c2orf48 was detected in C666-1, a classical cell line of human nasopharyngeal carcinoma (NPC)." (PMID 28906488, 2017). "RRM2‐C2orf48 chimeric transcript is highly expressed in human nasopharyngeal carcinoma (NPC), and it is speculated to be an effective predictor of NPC metastasis potential." (PMID 38321787, 2024).
oropharyngeal carcinoma (5 papers, 2009 to 2020). Carcinoma, predominantly squamous cell, arising from the epithelial cells of the oropharynx. "Overexpression of RRM2 has been demonstrated to correlate with an increase in cell invasive potential in a human KB oropharyngeal carcinoma cell line." (PMID 24637958, 2014). "Two human oropharyngeal carcinoma KB cell lines: KB-M2-D, which was forced to overexpress RRM2 protein by gene transfer, and KB-HURs, which was induced to overexpress RRM2 protein by hydroxyurea, were established." (PMID 19250552, 2009). "Furthermore, RRM2 can enhance angiogenesis by upregulating VEGF in oropharyngeal carcinoma cells, and thus anti-angiogenic and anti-tumor effects are anticipated following RRM2 inhibition." (PMID 31590218, 2019). "A role for RRM2 in blood vessels has not been documented, but it can enhance angiogenesis by upregulating VEGF in oropharyngeal carcinoma cells." (PMID 23056178, 2012).
pancreatic ductal adenocarcinoma (5 papers, 2013 to 2024). An infiltrating adenocarcinoma that arises from the epithelial cells of the pancreas. "For instance, RRM2 enhances cellular invasiveness by NF-kB-induced MMP-9 activation in pancreatic ductal adenocarcinoma." (PMID 27801665, 2016). "Finally, defective processing of let-7a precursors with a positive correlation to RRM2 overexpression was identified in patient-derived pancreatic ductal adenocarcinoma (PDAC) tissues." (PMID 23335963, 2013).
thyroid cancer (5 papers, 2018 to 2025). "(2016) found that RRM2 protein expression was up-expressed in undifferentiated thyroid cancer samples." (PMID 30386706, 2018). "Based on the risk score model of glutathione metabolism-related enzyme genes in thyroid cancer, in a further correlation analysis, we screened the target gene RRM2, whose high expression was significantly and negatively correlated with disease-free survival of patients, from nine candidate genes." (PMID 41333212, 2025). "Notably, in THCA, RRM2 also showed significant high expression (p.adj=4.90×1043), which may suggest a tumor-promoting role for RRM2 in thyroid cancer." (PMID 41333212, 2025).
triple-negative breast carcinoma (5 papers, 2013 to 2022). An invasive breast carcinoma which is negative for expression of estrogen receptor (ER), progesterone receptor (PR), and human epidermal growth factor receptor 2 (HER2). "Besides, we found that RRM2 was strongly elevated in basal-like subtype with respect to non-basal-like subtype; the same pattern of change was also observed in triple-negative breast cancer (TNBC) patients." (PMID 30898978, 2019).
vitiligo (5 papers, 2021 to 2024). Generalized well circumscribed patches of leukoderma that are generally distributed over symmetric body locations and is due to autoimmune destruction of melanocytes. "In vitiligo lesions, the upregulation of the RRM2 gene activates the NF-κB signaling pathway, leading to increased inflammation and melanocyte damage." (PMID 39430757, 2024). "Further investigations have revealed that in vitiligo lesions, the upregulation of the ferroptosis-related gene RRM2 activates the NF-κB signaling pathway." (PMID 39430757, 2024). "This study shows that CKS2 and RRM2 have potential as biomarkers of vitiligo and provides a theoretical basis for a better understanding of the pathogenesis of vitiligo." (PMID 36401415, 2022). "Another study found that the expression of RRM2 was upregulated in the skin lesions of vitiligo, and its 3’-UTR region had an miR-211 binding site, further verifying that RRM2 could be used as an effective marker of vitiligo." (PMID 36401415, 2022). "Therefore, CKS2 and RRM2 could be used as potential markers for vitiligo." (PMID 36401415, 2022). "Based on the 3D structure of the RRM2 protein, computer-assisted molecular docking predicted MB, an FDA-approved external skin medication for patients with vitiligo, as a potential inhibitor of RNR." (PMID 36230632, 2022). "Further immune infiltration analysis showed that M2 macrophages were involved in the pathogenesis of vitiligo, whereas CKS2 and RRM2 were both related to M2 macrophages." (PMID 36401415, 2022). "Previous study identified that microRNA-211 and its target genes (e.g. RRM2, TAOK1) regulated oxidative phosphorylation and energy metabolism and represented potential therapeutic targets for vitiligo." (PMID 34603063, 2021). "In addition, putative target genes of miR-211 such as PPARGC1A, RRM2, and TAOK1 are highly upregulated in Vitiligo, which is a pigmentation disorder." (PMID 39409187, 2024).
fibrosarcoma (4 papers, 2019 to 2025). A malignant mesenchymal fibroblastic neoplasm affecting the soft tissue and bone. "However, more studies using clinical fibrosarcoma patient samples and in vivo animal models are needed to uphold the association of piR-39980 and its two targets, RRM2 and CYP1A2, with positive responses of fibrosarcoma patients to DOX." (PMID 34799689, 2021). "piR-39980, a fibrosarcoma tumor suppressor, inhibits ribonucleoside-diphosphate reductase subunit M2 (RRM2) expression by binding to its 3'UTR, thus exerting an anti-tumor effect." (PMID 38993562, 2024). "piR-39980, a fibrosarcoma tumor suppressor, inhibits ribonucleoside-diphosphate reductase subunit M2 (RRM2) expression by binding to its 3′-UTR." (PMID 31399034, 2019). "Similarly, piR-39980 targeted RRM2 (ribonucleoside–diphosphate reductase subunit M2) mRNA 3′ UTR to inhibit cell proliferation of HT1080 fibrosarcoma cells." (PMID 41154843, 2025). "This study reveals that piR-39980 could reduce fibrosarcoma resistance to DOX by modulating RRM2 and CYP1A2, implying that piRNA can be used in combination with DOX." (PMID 34799689, 2021). "More specifically, we demonstrated that RRM2 and CYP1A2 play a vital role in the resistance of human fibrosarcoma to DOX." (PMID 34799689, 2021). "Our finding showed that piR-39980 could attenuate the DOX resistance by repressing the expression of RRM2 and CYP1A2 in DOX-resistant fibrosarcoma cells and hence could be a potential therapeutic agent for improving the clinical response of fibrosarcoma patients to DOX." (PMID 34799689, 2021).